POU2F3 (POU class 2 homeobox 3)
Description:
Transcription factor that binds to the octamer motif (5'-ATTTGCAT-3') and regulates cell type-specific differentiation pathways. Involved in the regulation of keratinocytes differentiation. The POU2F3-POU2AF2/POU2AF3 complex drives the expression of tuft-cell-specific genes, a rare chemosensory cells that coordinate immune and neural functions within mucosal epithelial tissues.
Synonyms: Oct-11; OTF-11; PLA1; OCT11; PLA-1; Skn-1a; Epoc-1
Tractability: Antibody: its Gene Ontology location is reachable by antibodies, with high confidence. PROTAC: ubiquitination databases record sites on it.
Gene: Protein-coding gene on chromosome 11 (120,236,640 to 120,319,945, forward strand). Ensembl gene ENSG00000137709.
Subcellular location: Nucleus
Subcellular location (Human Protein Atlas): Nucleoplasm; Cytosol; Plasma membrane
Gene Ontology:
Molecular function: DNA-binding transcription activator activity, RNA polymerase II-specific; protein binding; RNA polymerase II cis-regulatory region sequence-specific DNA binding; sequence-specific DNA binding; sequence-specific double-stranded DNA binding; DNA-binding transcription factor activity, RNA polymerase II-specific; DNA binding; DNA-binding transcription factor activity; identical protein binding
Biological process: host-mediated suppression of viral transcription; keratinocyte differentiation; positive regulation of transcription by RNA polymerase II; epidermis development; regulation of transcription by RNA polymerase II; cell differentiation; regulation of DNA-templated transcription
Cellular component: nucleoplasm; nucleus; chromatin; RNA polymerase II transcription regulator complex; transcription regulator complex
Genetic constraint (gnomAD): Loss-of-function variants: 22 observed, 54.4 expected, observed/expected ratio (o/e) 0.4, 90% interval 0.29 to 0.58. The upper end of that interval is the gene's LOEUF score, 0.58, which puts it in group 2 of 6, group 1 being the genes least tolerant of losing a copy. Missense variants: 461 observed, 541.64 expected, observed/expected ratio (o/e) 0.85, 90% interval 0.79 to 0.92. Synonymous variants: 184 observed, 216.8 expected, observed/expected ratio (o/e) 0.85, 90% interval 0.75 to 0.96.
Homologues: Orthologues: chimpanzee POU2F3 (99% identical), macaque POU2F3 (97% identical), pig POU2F3 (95% identical), rabbit POU2F3 (94% identical), dog POU2F3 (93% identical), mouse Pou2f3 (92% identical), rat Pou2f3 (91% identical), guinea pig POU2F3 (90% identical), tropical clawed frog pou2f3 (71% identical), zebrafish pou2f3 (59% identical). Paralogues in human: POU2F1 (50% identical), POU2F2 (50% identical), POU3F3 (32% identical), POU3F4 (31% identical), POU3F2 (29% identical), POU3F1 (28% identical), POU5F1 (25% identical), POU5F1B (24% identical), POU6F2 (24% identical), POU6F1 (23% identical), POU4F3 (23% identical), POU1F1 (23% identical), and 5 more.
Diseases named in the same sentence as POU2F3 in open-access papers:
POU2F3 is named in the same sentence as 96 diseases in open-access papers, as found by Europe PMC text mining. Sharing a sentence is not in itself a finding about the gene and the disease. The quoted sentences say what the papers report.
small cell lung carcinoma (25 papers, 2020 to 2026). Small cell lung cancer (SCLC) is a highly aggressive malignant neoplasm, accounting for 10-15% of lung cancer cases, characterized byrapid growth, and early metastasis. "In several cancer types, including small cell lung cancer, gastric cancer, and breast cancer, POU2F3 expression defines a distinct molecular subtype termed "tuft cell-like" tumors." (PMID 42211052, 2025). "Recent studies have identified mSWI/SNF (mammalian switch/sucrose non-fermentable) chromatin remodeling complexes as key regulators of POU2F3 expression in tuft cell-like small cell lung cancer (SCLC-P), highlighting a crucial lineage-specific dependency." (PMID 40333678, 2025). "POU2AF2 (previously known as C11orf53) is a protein-coding gene that acts as coactivator of the POU2F3 that regulates tuft cells in small cell lung cancer and colorectal cancer." (PMID 40506516, 2025). "In small cell lung carcinoma, transcription factors such as NEUROD1, achaete-scute family bHLH transcription factor 1 (ASCL1), POU class 2 homeobox 3 (POU2F3), and Yes1-associated transcriptional regulator (YAP1) are used for sub-classification." (PMID 39937015, 2025). "POU2AF3 (COLCA2) was described as a coactivator of POU2F3 in the cells and we used a small-cell lung cancer cell line (H526) as a control." (PMID 40134582, 2025). "Small cell lung cancer (SCLC) is frequently subdivided into four molecular subtypes according to the activity of key transcription factors (TF): NEUROD1, ASCL1, POU2F3, and YAP1 (NAPY)." (PMID 41732133, 2026). "Molecular subtypes of small cell lung cancer (SCLC) have been described based on differential expression of the transcription factors (TFs) ASCL1, NEUROD1, and POU2F3 and immune-related genes." (PMID 40305287, 2025). "In small cell lung cancer (SCLC), four molecular subtypes were classified based on the expression of master transcriptional regulators including ASCL1, NEUROD1, POU2F3, and YAP1." (PMID 40243428, 2025). "Tuft cells have attracted attention in oncology after the discovery of a tuft cell-like small cell lung cancer (SCLC) subset, which exhibits a tuft cell-like gene expression signature, including POU2F3, the tuft cell master regulator." (PMID 36402755, 2022). "Recent studies have reported that the subtypes of small cell lung cancer contained atonal bHLH transcription factor 1 (ATOH1), pOU class 2 homeobox 3 (POU2F3), neurogenic differentiation factor 1 (NEUROD1), and achaete–scute complex homolog-like (ASCL1)." (PMID 36551512, 2022). "We also wondered about the distribution of TRIT1 gene amplification according to the small-cell lung cancer molecular subtypes ASCL1, NEUROD1, POU2F3, and YAP1." (PMID 33919717, 2021). "POU2F3 expression is observed in a subset of small-cell lung cancers (SCLC-P) that display a non-neuroendocrine phenotype." (PMID 39858036, 2025). "Background/Objectives: Small-cell lung cancer (SCLC) is a highly aggressive malignancy with an emerging molecular classification based on the expression of the transcription factors ASCL1, NEUROD1, and POU2F3." (PMID 39682568, 2024). "Moreover, small cell lung cancer (SCLC) has been classified into four molecular subtypes, including ASCL1+, NEUROD1+, POU2F3+ and YAP1+ SCLC." (PMID 34722635, 2021). "Small-cell lung cancer (SCLC) is an aggressive malignant cancer that is classified into four subtypes based on the expression of the following key transcription and co-transcription factors: ASCL1, NEUROD1, YAP1, and POU2F3." (PMID 33202998, 2020). "For comparison, we also collected EVs secreted by a non‐small cell lung cancer cell line (A549) and human bronchial epithelial cells (HBEC) as negative controls, as these cells lack ASCL1, NEUROD1, and POU2F3 expression." (PMID 40285610, 2025). "Despite recent progress in subtype classification for small cell lung carcinoma (SCLC), little is known about the biomarker for triple‐negative (ASCL1, NEUROD1, and POU2F3 negative) tumors." (PMID 37789961, 2023).
prostate carcinoma (6 papers, 2021 to 2024). A carcinoma that arises from epithelial cells of the prostate gland. "Taken together, these findings suggest that POU2F3 is more likely to serve as a master TF for NEtD in prostate cancer, while in SCLC, it is more pronounced as a non‐NE TF." (PMID 39372390, 2024). "In prostate cancer, POU2F3 expression is observed in both CRPC and NEPC, and it appears to be mutually exclusive with ASCL1." (PMID 39372390, 2024). "Recent studies of castration resistant prostate cancer and its subtype, neuroendocrine prostate cancer, revealed Pou2f3+ populations in mouse models." (PMID 37386128, 2023). "Finally, we investigated the expression levels of POU2F3 in prostate cancer patients." (PMID 34099734, 2021). "To validate the expression of POU2F3 at the protein level, we performed POU2F3 immunohistochemistry on a tissue microarray (TMA) of prostate cancer cases containing evaluable material for 22 CRPC patients and 8 NEPC patients." (PMID 34099734, 2021).
cervical cancer (5 papers, 2013 to 2021). A primary or metastatic malignant neoplasm involving the cervix. "A colony inhibition assay showed that human POU2F3 overexpression inhibited the proliferation of cervical cancer cell lines of epithelial origin." (PMID 31893322, 2020). "POU2F3 is a transcription factor that has been largely silenced in cervical cancer and has been highlighted as a tumor suppressor gating the transformation of primary cell lines to metastatic melanomas." (PMID 24204564, 2013). "In addition, Pou2f3 has been suggested as a tumor suppressor gene, which was downregulated in cervical cancer and melanoma." (PMID 33664254, 2021). "It had been reported that human POU2F3 could promote keratinocyte proliferation, however, the knockout mice study and the colony inhibition assay in cervical cancer cells suggested POU2F3 might inhibit keratinocyte proliferation." (PMID 31893322, 2020). "In addition, POU2F3 was also reported might be a cancer-related tumor suppressor in both intraepithelial neoplasia and cervical cancer, highlighted the importance of POU2F3 in bladder squamous cell carcinoma." (PMID 27602771, 2016). "Besides, down-regulation of POU2F3 was reported correlated to the process of both cervical intraepithelial neoplasia (CIN) and cervical cancer (CC)." (PMID 27602771, 2016).
lung adenocarcinoma (4 papers, 2021 to 2023). A carcinoma that arises from the lung and is characterized by the presence of malignant glandular epithelial cells. "There were shared somatic mutations as well as POU2F3 in the adenocarcinoma and SCLC, suggesting that POU2F3 can derive from the same cell as lung adenocarcinoma." (PMID 35954436, 2022). "In contrast, most NKX2-1-positive human lung adenocarcinomas were entirely POU2F3-negative (44/51)." (PMID 33821796, 2021).
lung carcinoma (4 papers, 2021 to 2023). "This expands upon other recent observations that POU2F3 can be upregulated in specific subtypes of lung cancer." (PMID 33821796, 2021). "Recent studies have discovered molecular subtypes of SCNE lung cancer defined by ASCL1 (achaete-scute family bHLH transcription factor 1), NEUROD1 (neurogenic differentiation 1), POU2F3 (POU class 2 homeobox 3), and YAP1 (Yes1 associated transcriptional regulator) transcription factors." (PMID 37467967, 2023). "Thus, the therapeutic strategy that aims at blocking POU2F3 function or ablating the tuft cell lineage is expected to have a wide therapeutic scope for patients with tuft cell-like lung cancers." (PMID 36569325, 2022). "Tuft cell-like tumors with co-expression of POU2F3, GFI1B, and KIT were identified among pulmonary squamous cell carcinomas, adenocarcinomas, and large cell neuroendocrine carcinoma, and new molecular subsets were delineated by their tuft cell-like signatures among the lung cancer histotypes." (PMID 36569325, 2022).
small cell carcinoma (4 papers, 2024 to 2025). A neuroendocrine carcinoma composed of small malignant cells which are often said to resemble "oat cells" under the microscope. "POU2F3 is a regulator of tuft cell differentiation expressed in multiple malignancies including thymic squamous cell carcinoma and a subset of small cell carcinoma." (PMID 40242668, 2025). "The lack of apparent NE differentiation is supported by the absence of ASCL1, NEUROD1, and POU2F3, which are all transcription factors associated with small cell neuroendocrine carcinomas, including NEPC." (PMID 38667288, 2024). "Moreover, the therapeutic efficacy of mSWI/SNF ATPase degraders in SCLC-P suggests broader implications whereby other POU2F3-expressing small cell carcinomas may respond to this targeted therapy." (PMID 38328238, 2024). "POU2F3-driven small cell carcinomas are biologically distinct, characterized by the absence of classic neuroendocrine lineage markers, including synaptophysin, chromogranin and INSM1 and the expression of tuft cell lineage markers." (PMID 40931642, 2025).
large cell neuroendocrine carcinoma (3 papers, 2022 to 2023). A usually aggressive carcinoma composed of large malignant cells which display neuroendocrine characteristics. "Our findings add these tumor types to a growing list of neoplasms that can show POU2F3 immunoreactivity, including pulmonary small cell carcinoma, large cell neuroendocrine carcinoma, and basaloid squamous cell carcinoma." (PMID 37190202, 2023).
pancreatic cancer (3 papers, 2020 to 2024). "CD11b-expressing cells are definitely more present in the PKI;POU2F3+/+ tumors since we clearly see the infiltration among the stroma as foci at the edge of the high grade PanIN as observed in the PKI;POU2F3+/+ pancreatic tumors." (PMID 33086657, 2020). "Regulate cluster cell development and stem cell characteristics of pancreatic cancer cells by increasing the expression of DCLK1, POU2F3, ALDH1A1, and IL17RC." (PMID 39906741, 2024). "IL-17 could also regulate cluster cell development and stem cell characteristics of pancreatic cancer cells by increasing the expression of DCLK1, POU2F3, ALDH1A1, and IL17RC." (PMID 39906741, 2024). "In pancreatic tumors, it has recently been shown that immune cell-derived IL-17 regulates the development of TCs via increased expression of DCLK1, POU domain class 2 transcription factor 3 (POU2F3), aldehyde dehydrogenase 1 family member A1 (ALDH1A1), and IL17RC." (PMID 33348546, 2020).
thymic carcinoma (3 papers, 2023 to 2025). Thymic carcinoma (TC) is a type of thymic epithelial neoplasm characterized by a high malignant potential. "We also caution that EZH2 and POU2F3 are detectable in non-thymic carcinomas, and immunoreactivity for these markers does not imply thymic origin." (PMID 37190202, 2023). "EZH2 and POU2F3 immunohistochemistry may therefore be useful for distinguishing thymic carcinoma from thymoma." (PMID 37190202, 2023). "We assessed whether immunohistochemistry for two proteins, EZH2 and POU2F3, could distinguish thymic carcinoma and thymoma." (PMID 37190202, 2023). "As proposed previously, the presence of POU2F3 immunoreactivity may indicate the acquisition of a tuft cell phenotype by thymic carcinomas." (PMID 37190202, 2023). "We explored the relationship between CD5, CD117, EZH2, POU2F3, MTAP, and BAP1 immunoreactivity and the overall survival (OS) and progression-free survival (PFS) of patients with thymic carcinoma, using a cohort with diverse histologic subtypes." (PMID 40242668, 2025). "CD5, CD117, EZH2, POU2F3, MTAP, and BAP1 have been proposed as useful markers for the distinction of thymic carcinoma from thymoma." (PMID 40242668, 2025). "We aimed to determine the prognostic significance of CD5, CD117, EZH2, POU2F3, BAP1, and MTAP immunohistochemical staining in thymic carcinomas." (PMID 40242668, 2025). "Whole slide sections of 37 thymic carcinomas, 23 type A thymomas, 13 type B3 thymomas, and 8 micronodular thymomas with lymphoid stroma (MNTLS) were immunostained for EZH2, POU2F3, CD117, CD5, TdT, BAP1, and MTAP." (PMID 37190202, 2023).
thymoma (3 papers, 2021 to 2023). A neoplasm arising from the epithelial cells of the thymus. "As tuft cells exist in the thymic medulla, the presence of rare POU2F3 positive cells in type A thymomas and MNTLS may be consistent with a medullary origin of these tumors." (PMID 37190202, 2023). "In addition, SOX9 expression was positively associated with POU2F3 and TRPM5 expressions, the master regulators of tuft cells, suggesting that high SOX9 expression might be associated with the tuft cell phenotype of thymomas." (PMID 34778027, 2021). "One study using tissue microarrays found moderate to strong POU2F3 staining in >40% of tumor cells in 72% (18/25) of thymic squamous cell carcinomas, 8% (1/12) of type B3 thymomas, and none (0/10) of the type A thymomas." (PMID 37190202, 2023).
breast carcinoma (2 papers, 2023 to 2025). "Given these limitations, future studies should delineate the clinical, pathological, and molecular features of POU2F3-positive or tuft cell-like breast cancers." (PMID 37179317, 2023). "POU2F3 expression defines small subsets in various breast cancer subtypes, which can be accompanied by DCIS." (PMID 37179317, 2023). "The frequency of POU2F3-positive breast cancers was lower than expected in our new invasive breast carcinoma TMA cohort (0.22%)." (PMID 37179317, 2023). "Two TNBCs of the four previously reported invasive POU2F3-positive breast cancers contained POU2F3-positive ductal carcinoma in situ (DCIS)." (PMID 37179317, 2023). "Indeed, one of our POU2F3-positive breast cancers (the only case for which SOX9-IHC was available) clearly expressed SOX9." (PMID 37179317, 2023). "Obvious candidate precursors of POU2F3-positive breast cancers could be the (eventually committed) precursors of the rare POU2F3-positive cells in the normal breast." (PMID 37179317, 2023). "In light of this hypothesis, in-depth characterization of physiological POU2F3-expressing mammary cells and their precursors appears as a research priority to gain insight into the carcinogenesis of POU2F3-positive breast cancers." (PMID 37179317, 2023). "We then compared the distribution of POU2F3-positive cells and cells expressing ER, CK5 (a basal marker), and oncogenes often expressed in tuft cell-like cancers (BCL2 and KIT) to ask whether the POU2F3-positive cells had a phenotype similar to tuft cell-like breast cancers." (PMID 37179317, 2023). "To find out whether POU2F3 was also expressed in the respective “non- or pre-invasive” lesion, i.e., ductal carcinoma in situ (DCIS), we investigated full-face sections of the previously identified four invasive POU2F3-positive breast cancer cases." (PMID 37179317, 2023). "This hypothesis would explain the paucity of POU2F3-positive breast cancers compared with the more frequent luminal-type and HER2-positive/HR-negative breast cancers that are derived from the much more abundant POU2F3-negative epithelial cells." (PMID 37179317, 2023). "We believe tuft cell-like properties, particularly those related to POU2F3 and SOX9, in neoplastic and non-neoplastic breast tissues are worth further investigation and may be key to dissecting the complex biology of breast cancers, particularly TNBCs." (PMID 37179317, 2023).
colitis (2 papers, 2025). Inflammation of the colon. "Notably, recent work has implicated TET2/3 as critical mediators of the response of mice to chemically induced colitis by regulation of POU2F3-methylation and SI tuft cell abundance, further supporting the importance of this cell-type in governing immune response in gut." (PMID 39609081, 2025).
COVID-19 (2 papers, 2022 to 2025). A disease caused by infection with severe acute respiratory syndrome coronavirus 2. "Similar to the EBC-derived tuft cells in influenza-infected mice, the ectopic tuft cells in the parenchyma of COVID-19 lungs co-expressed KRT5 and POU2F3, suggesting a similar differentiation scheme." (PMID 36129169, 2022).
helminth infection (2 papers, 2021 to 2022). "Skn1a/Pou2f3-deficient mice lack intestinal tuft cells and have defective mucosal type 2 responses to helminth infection in the intestine." (PMID 33781205, 2021).
influenza (2 papers, 2022). An acute viral infection of the respiratory tract, occurring in isolated cases, in epidemics, or in pandemics; it is caused by serologically different strains of viruses (influenzaviruses) designated A, B, and C, has a 3-day incubation period, and usually lasts for 3 to 10 days. "We found that in Pou2f3-/-, Trpm5-/-, and Il4ra-/- animals, the percent of Agr2+ area within Krt5+ area was not significantly different from controls following influenza infection." (PMID 36073526, 2022).